CD48 (CD48 molecule)
Diseases named in the same sentence as CD48 in open-access papers (continued):
Sharing a sentence is not in itself a finding about the gene and the disease.
asthma (9 papers, 2017 to 2025). "CD48 is a costimulatory receptor associated with human asthma." (PMID 30306094, 2018). "The levels of CD48 soluble form, sCD48, were higher in the serum of mild asthmatic patients and reduced in moderate and severe asthma." (PMID 34658882, 2021). "The evidence supporting the involvement of CD48 in allergic diseases comes mainly from murine models for asthma." (PMID 30306094, 2018). "These include CD44, a hyaluronan receptor, and CD48, whose levels are lower in poorly controlled or severe asthma compared to well-controlled or moderate disease." (PMID 28660189, 2017). "A possible explanation for this phenomenon is a high degree of ongoing extravasation of the most activated eosinophils, i.e., those with the highest level of CD44, CD48, and β1 integrin activation, in severe asthma." (PMID 28660189, 2017). "Moreover, eosinophils from nasal polyps and asthmatic patients’ blood also showed increased CD48 expression, while another study reported elevated CD48 expression in moderate asthma and reduced levels in severe asthma." (PMID 39682685, 2024). "Previous studies assessing the significance of CD48 in asthma have not evaluated the relation to type 2 associated biomarkers and CD48." (PMID 30306094, 2018). "We regarded these cytokines as potential markers that will help clarify CD48's role in airway inflammation in asthma and as markers that may help assess the degree of inflammation in our patients." (PMID 30306094, 2018). "The roles of CD48 as a costimulatory receptor of various immune responses, its involvement in allergen-induced airway inflammation, and its regulation in mice by ORMDL3 have strongly implicated CD48 association to human asthma." (PMID 30306094, 2018). "Some new markers may be useful in severe asthma including airway and peripheral urokinase plasminogen activator receptor and CD48 on blood leukocytes." (PMID 30498567, 2018). "Interestingly, CD48 has also been identified as a soluble form in human serum, and shown to be at increased levels in patients with arthritis, mild asthma, and advanced lymphoid malignancies, potentially acting as an antagonist or decoy receptor capable of blocking CD48:2B4 binding." (PMID 30947296, 2019). "Therefore, CD48 might be a good candidate as a biomarker for different degrees of asthma severity." (PMID 34658882, 2021). "We have shown that CD48 participates in allergic eosinophilic airway inflammation and is a potential target for the suppression of asthma in mice, but it has also been shown that CD48 participates in nonallergic respiratory inflammatory processes." (PMID 30306094, 2018). "We aimed to assess the significance of the soluble form of CD48 (sCD48) in allergic and nonallergic asthma." (PMID 30306094, 2018). "Thus, even though CD48 seems to be involved in airway inflammation in patients with nonallergic asthma, its exact inflammatory function is still unclarified." (PMID 30306094, 2018). "Thus, no clinical information was available about the relation of CD48 to different types of inflammatory processes in patients with asthma." (PMID 30306094, 2018). "The multiple immune functions of CD48, its upregulation in both allergic and nonallergic, inflammatory conditions and viral and bacterial infections, have led us to speculate that sCD48 may be used as a marker for both allergic and nonallergic asthma." (PMID 30306094, 2018). "Furthermore, previous studies have shown that neutralization of CD48 significantly reduced proinflammatory cytokine expression thus elevated sCD48 levels in patients with nonallergic asthma may presumably be related to an increased inflammatory state." (PMID 30306094, 2018). "Several proteins, including CD45, CD45R0, CD48, CD137, IL-17 receptor (R) A and B, αL integrin, and some of the Fc receptors, are increased or decreased on circulating eosinophils in asthma compared to normal, non-allergic healthy individuals." (PMID 28660189, 2017).
viral infections (9 papers, 2009 to 2025). "In agreement with this, many viral infections appear to adopt this mechanism, such as cytomegalovirus which showed a reduced CD48 expression by macrophages thus hindering itself from NK cells." (PMID 40610562, 2025). "The mucin-like protein m153 in murine cytomegalovirus (CMV) has been shown to reduce expression of CD48 on macrophages, limiting NK-cell-mediated control of viral infection." (PMID 34142199, 2021). "Previous works have shown a variation of CD48 expression with viral infections; downmodulation on HIV-infected and upregulation on EBV infected cells." (PMID 24505299, 2014). "Although CD48 is broadly expressed on hematopoietic cells including lymphocytes and monocytes, viral infection such as HIV or EBV has been shown to decrease or increase CD48 expression on the infected cell, respectively." (PMID 19997502, 2009). "In summary, we propose that A43 may serve as a functional soluble CD48 decoy receptor by binding and masking 2B4, thereby impeding effective NK cell immune control during viral infections." (PMID 30947296, 2019). "Genes involved in defense response to bacterial or viral infections such as BPIFA2, CD48, ULBP3, NKG2D ligand 1-like, and NKG2D ligand 4-like were reported to have more copies in the genomes of Nubian ibex relative to the domestic goat reference." (PMID 34142199, 2021). "Its ligand is CD48, and the CD244/CD48 interaction regulates target cell lysis by NK cells and CD8+ cytotoxic T cells, in addition to participating in the fight against viral infection and regulation of effector/memory T cell generation and survival." (PMID 31138840, 2019).
COVID-19 (8 papers, 2021 to 2025). A disease caused by infection with severe acute respiratory syndrome coronavirus 2. "Studies have shown that the CD48 expression levels are elevated in the blood of COVID-19 patients and correlate with the infection progression." (PMID 36551164, 2022). "These transcriptomic profiles suggest that BALF FCN+ and FCN+SPP1+ macrophage clusters predominant in severe COVID-19 shared pathogenic molecular pathways, including the expression of their signature mediators S100A12 and SPP1 with ST CD48hiS100A12+ and CD48+SPP1+ clusters predominant in active RA." (PMID 34143756, 2021). "Moreover, the QTL overlap and colocalization analyses showed that the genetic signal associated with increased severe COVID-19 risk also modulated immune genes (i.e., PDDC1, CD150, CD48) in monocytes." (PMID 34027315, 2021). "In fact, patients with COVID-19 presented the upregulation of T cell markers, such as CD4, CCL21, CD48 and TNFRSF1B/TNFR2." (PMID 37047248, 2023). "COVID-19 BALF FCN1+ and FCN1+SPP1+ macrophage clusters are transcriptionally similar to CD48hiS100A12+ and CD48+SPP1+ clusters that drive RA synovitis." (PMID 34143756, 2021). "The BALF FCN1+ and FCN1+SPP1+ macrophage clusters from severe COVID-19 patients shared transcriptomic profiles with STM CD48hiS100A12+ and CD48+SPP1+ clusters from active RA, respectively." (PMID 34143756, 2021). "We also found an increased expression of CD63, ITGB2, CD37, CD2 and IL23R markers and the reduction in CXCR4, CD69, CD48, ICAM1 and S100A10 markers in COVID-19-derived NK-T cells compared to controls." (PMID 34944610, 2021). "In COVID-19+ patients, we found a strong correlation between GDF-15 and soluble CD48 levels." (PMID 38686386, 2024). "We found that bronchoalveolar lavage fluid (BALF) macrophage clusters FCN1+ and FCN1+SPP1+ predominant in severe COVID-19 were transcriptionally related to synovial tissue macrophage (STM) clusters CD48hiS100A12+ and CD48+SPP1+ that drive rheumatoid arthritis (RA) synovitis." (PMID 34143756, 2021). "The hierarchical analysis and comparison of cluster markers also indicate a shared transcriptional profile of COVID-19 FCN1+SPP1+ and synovitis CD48+SPP1+ clusters consisting of 86 common marker genes including SPP1, which have broad proinflammatory and fibrotic functions." (PMID 34143756, 2021).
autoimmune disease (7 papers, 2015 to 2025). A disorder resulting from loss of function or tissue destruction of an organ or multiple organs, arising from humoral or cellular immune responses of the individual to their own tissue constituents. "The CD2/CD58/CD48 pathway is associated with the human autoimmune diseases multiple sclerosis and rheumatoid arthritis and with a model of murine lupus." (PMID 26438525, 2015). "Moreover, the THBS network, whose ligand is highly expressed after LPS stimulation, increases the risk of inflammation, and the CD48 network, which is known to activate NK cells and contribute to diverse autoimmune diseases, is maintained even after periodontal therapy." (PMID 36329504, 2022). "As an immune co-stimulatory and adhesion molecule, CD48 contributes to autoimmune disease regulation, suggesting a potential role in pSS via immune response modulation." (PMID 41476962, 2025). "Moreover, the CD2/CD58 pathway is associated with the human autoimmune diseases, multiple sclerosis, and rheumatoid arthritis, and the CD2/CD48 pathway is associated with a model of murine lupus." (PMID 26438525, 2015). "In the context of autoimmune diseases, CD244/CD48 co-stimulatory signals are primarily involved in regulating immune cell functions and influencing episodes of autoimmune disease." (PMID 38980684, 2025). "Among them, TGFBR1, TGFBR2, CCL5, CD48, CD244A, and CD72 have been reported to be closely related to the pathophysiologic processes of autoimmune diseases." (PMID 35515003, 2022). "Many of these genes have either known roles in Treg differentiation, stability and function (CD48, IL6ST, EZR, ELMO1, IL18R1), or altered expression in human Treg in autoimmune disease (SLAMF1, ANKRD55, TAGAP)." (PMID 35773720, 2022). "Thus, considering the exceptional binding kinetic features of A43 compared to human CD48, one key aspect derived from this work is the potential of using A43 to develop novel therapeutic tools to manipulate aberrant immune responses, such as autoimmune diseases." (PMID 30947296, 2019).
melanoma (7 papers, 2018 to 2024). A malignant, usually aggressive tumor composed of atypical, neoplastic melanocytes. "Transfected CD48+ B16 melanoma cells were poorly rejected by wild-type (WT) mice, suggesting that the expression of CD48 on tumor cells inhibits the killing of B16 cells." (PMID 32630303, 2020). "In both of these studies, CD244−/− mice demonstrated increased ability to reject CD48(+) B16 melanoma cells compared with WT." (PMID 30546369, 2018). "However, female CD244−/− mice showed poor rejection of both CD48(+) and CD48(–) B16 melanoma cells, suggesting a gender-based difference in these genetically-modified mice." (PMID 30546369, 2018). "According to the melanoma SCRS data, all mir-149 targets identified were expressed in lymphocytes, some of which were exclusively expressed in this cell type and include CD96, CD48, SLAMF7, FASLG, NUGGC and NLRC5." (PMID 32024530, 2020).
Allergy (5 papers, 2018 to 2023). An allergy is an immune response or reaction to substances that are usually not harmful. "The same study reported that a CD48 antagonist (neutralizing monoclonal antibody [mAb]) induced a significant reduction in SA adherence and its intracellular localization in CD48-deficient (CD48-/-) mice, which could be used to treat allergy." (PMID 36993982, 2023). "This leads to the conclusion that CD244 is critical for the initiation and continuation of allergic status, and that blockade of either CD244 or CD48 is a promising therapeutic strategy for treatment of allergic diseases." (PMID 33841431, 2021). "Clinically, membrane and soluble CD48 expression increases under inflammatory conditions and has been shown to be elevated in patients with systemic inflammatory disorders, hematopoietic malignancies, infections, and allergic diseases." (PMID 30306094, 2018). "However, more studies of allergic diseases concentrated on CD48 rather than CD244." (PMID 33841431, 2021).
lupus (5 papers, 2013 to 2017). "We next found that the changes in expression of nine of these twelve adhesion molecules were significantly upregulated on brain-infiltrating CD8+ T cells in TLR7[Tg] lupus-prone mice; namely CD49d, CD11a, CD31, CD54, CD49f, CD29, CD48, and CD43aag, as well as CD44 and CD103." (PMID 28098193, 2017).
acute myeloid leukemia (4 papers, 2021 to 2025). Acute myeloid leukemia (AML) is a group of neoplasms arising from precursor cells committed to the myeloid cell-line differentiation. "Our study also highlighted the downregulation of immune-activating molecules, such as CD48, which has been linked to decreased NK cell-mediated cytotoxicity, as reported in acute myeloid leukemia." (PMID 39860532, 2025). "In acute myeloid leukemia (AML), HO-1 has also been described to prevent cytotoxic effects of NK by inhibiting CD48 expression, a ligand of the NK-activating receptor 2B4, through Sirt1-H3K27-dependent pathway." (PMID 39611159, 2024).
Arthritis (4 papers, 2005 to 2025). Inflammation of a joint. "In addition to membrane-bound CD48, soluble CD48 has been detected in blood, with increased levels observed in lymphoproliferative diseases, Epstein-Barr virus infection, and arthritis." (PMID 40597436, 2025).
rheumatoid arthritis (4 papers, 2015 to 2025). A chronic, systemic autoimmune disorder characterized by inflammation in the synovial membranes and articular surfaces. "Similarly, we identified relevant protein associations for cg19693031 (TXNIP gene) previously associated with type 2 diabetes and cg07839457 (NLRC5 gene) previously associated with immune-related proteins such as CD48 antigen or traits such as rheumatoid arthritis." (PMID 41361833, 2025). "It is particularly noteworthy that expression levels of CD48 and TIGIT were significantly lower in patients with rheumatoid arthritis compared to those with pSS." (PMID 41476962, 2025).
B cell lymphoma (3 papers, 2023 to 2025). "Top proteins that were consistently associated with B-cell lymphoma across the EPIC, ARIC and UK Biobank cohorts included: CXCL13, sCD23, FCRL1, FCRL3, SEMA7A, CD72, CD48, LY9 and VCAM1." (PMID 40894013, 2025). "SLAMF2/CD48 was originally termed B-LAST 1 and found in B cells transformed with EBV virus and in neoplastic B cells in approximately 80% of chronic lymphocytic leukemia cases and 50% of poorly differentiated B cell lymphoma cases." (PMID 38612827, 2024).
osteosarcoma (3 papers, 2023 to 2025). A usually aggressive malignant bone-forming mesenchymal neoplasm, predominantly affecting adolescents and young adults. "CD48, TIMD-4, B7-H6, CD134, B7-H5, CD47, and S100A8/A9 were significantly elevated in osteosarcoma patients, each linked to increased osteosarcoma risk." (PMID 40963634, 2025). "With the exception of B7-H2, all measured immune checkpoint proteins—CD48, TIMD-4, B7-H6, CD134, B7-H5, CD47, and S100A8/A9—were significantly elevated in osteosarcoma patients compared to healthy controls (p < 0.05)." (PMID 40963634, 2025).
Sepsis (3 papers, 2017 to 2024). Sepsis is defined as life-threatening organ dysfunction caused by a dysregulated host response to infection. "We thus used CD48 staining to assay the MDSC subsets in our sepsis model." (PMID 28337051, 2017).
acute myocardial infarction (2 papers, 2024 to 2025). Necrosis of the myocardium, as a result of interruption of the blood supply to the area. "A recent bioinformatics study identified CD48 as a candidate diagnostic biomarker for acute myocardial infarction (AMI), highlighting its potential utility in early diagnosis and risk stratification." (PMID 41019764, 2025). "Acute myocardial infarction (AMI) and CD48 have not been linked conclusively by any studies to date." (PMID 38783198, 2024). "Similar to CD48, CD247 and Acute Myocardial Infarction (AMI) have not been conclusively linked by research." (PMID 38783198, 2024).
anemia (2 papers, 2016 to 2024). A reduction in the number of red blood cells, the amount of hemoglobin, and/or the volume of packed red blood cells. "In this study, we found that systemic USP10-KO mice develop BM failure with pancytopenia including severe anemia, which is caused by the severe reduction of LT-HSCs (CD150+CD48− LSK) in FL and BM." (PMID 27974222, 2016). "Low high density lipoprotein (HDL) has frequently been associated with untreated CD47, and the combination of unexplained iron-deficiency anemia and low HDL may be particularly suggestive of CD48." (PMID 39730479, 2024).
Autoimmunity (2 papers, 2018 to 2023). The occurrence of an immune reaction against the organism's own cells or tissues. "CD48 has numerous roles in the regulation of immunity and has been shown to be elevated in patients with hematopoietic malignancy, infections, and inflammatory diseases with autoimmunity." (PMID 30306094, 2018). "CD48 is also a candidate molecular target for controlling not only HLH but also autoimmunity, and cancer." (PMID 37187762, 2023).
colon cancer (2 papers, 2023 to 2025). "The results showed that PDCD1LG2, ICOS, CD86, CD80, CD48, and CD274 showed a significant exclusion situation from RFX1 expression in colon cancer." (PMID 41425715, 2025).
diabetic nephropathy (2 papers, 2023). "Diabetic nephropathy pathogenesis involves an inflammatory response, cell death, immune response, etc., so CD48 may promote the cascade effect of the inflammatory response through humoral immune regulation, accelerating the progression of diabetic nephropathy." (PMID 38028597, 2023). "This bioinformatics analysis identified four disulfidptosis-related genes (CXCL6, CD48, C1QB, and COL6A3) with high diagnostic value and their expression may be closely related to the declined renal function in diabetic nephropathy." (PMID 38028597, 2023). "This study identified four key genes (CXCL6, CD48, C1QB, and COL6A3) involved in diabetic nephropathy using a series of bioinformatics methods." (PMID 38028597, 2023). "In the volcano plot, CXCL6, CD48, C1QB, and COL6A3 are all highly expressed in diabetic nephropathy patients, with areas under the ROC curve of 0.908, 0.928, 0.907, and 0.895, respectively." (PMID 38028597, 2023). "The intersection of the two algorithms obtained four key genes for diabetic nephropathy (CXCL6, CD48, C1QB, and COL6A3) which were used to construct the nomogram." (PMID 38028597, 2023). "Thus, monitoring CXCL6, CD48, C1QB, and COL6A3 expression can help in the diagnosis of diabetic nephropathy." (PMID 38028597, 2023). "Our study explored the same platform GEO dataset for diabetic nephropathy bioinformatics analysis and identified eight potential key genes (TYROBP, ITGB2, CD53, IL10RA, LAPTM5, CD48, C1QA, and IRF8), screened eight transcription factors, and identified 93 miRNA nodes." (PMID 37113991, 2023). "The gradually decreasing glomerular filtration rate and increasing plasma creatinine with the increased expression of CXCL6, CD48, C1QB, and COL6A3 suggests that the deterioration of kidney function in diabetic nephropathy may be closely related to the expression of key genes." (PMID 38028597, 2023). "Thus, CXCL6, CD48, C1QB, and COL6A3 may be involved in kidney function deterioration in diabetic nephropathy patients." (PMID 38028597, 2023). "The expression of CXCL6, CD48, C1QB, and COL6A3 was higher in diabetic nephropathy patients than in normal controls, indicating that their expression is closely related to disease progression, so these key genes may be potential new therapeutic targets for diabetic nephropathy." (PMID 38028597, 2023).